STIM1 (stromal interaction molecule 1)
Diseases named in the same sentence as STIM1 in open-access papers (continued):
Sharing a sentence is not in itself a finding about the gene and the disease.
cancer (continued). "Limited data regarding the correlation of STIM1 and SOX2 in cancer and their possible synergistic impact." (PMID 38532463, 2024). "On the other hand, in cancer cells, such as colorectal cancer (CRC) cells, miR-185 blunts the expression of STIM1, thereby suppressing the metastasis and invasion of CRC." (PMID 37932320, 2023). "Given the critical role of STIM1 in activating the Ca2+ signaling pathway in cancer cells and the positive role of TSPAN18 in regulating STIM1, we tested the effect of TSPAN18 on the Ca2+ signaling pathway." (PMID 37542345, 2023). "This is a significant observation, as we investigated miR3653 expression in Huh-7 HCC CSC cells by enhancing STIM1 and Orai1 expression, which mimics poor cancer prognosis, instead of using parental EpCAM(-)/CD133(-) Huh-7 cancer cells." (PMID 36556285, 2022). "In the following, we will focus on STIM1 and STIM2, because only these two isoforms have been described as playing a role in cancer." (PMID 36612099, 2022). "Regarding the STIM1/Orai1-mediated SOCE, further studies aiming at developing potent and selective inhibitors that target cancer cell-specific microtubule-dependent STIM1 trafficking mechanism on SOCE activation will facilitate better therapeutic approaches." (PMID 35008759, 2021). "In addition to the role in calcium signaling in tumor cells, STIM1 is an important modulator of a wide variety of cellular programs in non-tumor cells within the tumor microenvironment, such as cancer-associated fibroblasts (CAFs), endothelial cells and immune cells." (PMID 33859736, 2021). "STIM1 act as Ca2+ sensor on the ER membrane and mediate SOCE, which was widely responsible for cell survival and death in various of cancer 36, 44-45." (PMID 33867841, 2021). "In thyroid follicular ML-1 cancer cells, SOCE was significantly decreased in both stable STIM1 (STIM1-KD) and ORAI1 (ORAI1-KD) knock-down cells, compared with control mock-transfected cells." (PMID 34155535, 2021). "Accumulating evidence has revealed that many cancers, such as breast, liver, lung, gastric, colon, and ovarian cancer, exhibit augmented SOCE and overexpression of STIM1 or ORAI1." (PMID 34122115, 2021). "Increasing evidence suggest that store-operated calcium entry (SOCE), mediated by the STIM1 and ORAI1 proteins, is a key player in regulating the pathophysiology of cancer." (PMID 34155535, 2021). "However, the issue of whether the different genetic variants of STIM1 lead to dissimilar consequences in the SOCE activation that modulates the behavior of cancer cells has not yet been studied." (PMID 34803742, 2021). "Stromal interaction molecule 1 (STIM1), a component of SOCE, is upregulated in several types of cancer and responsible for cancer cell migration, invasion, and metastasis." (PMID 35008585, 2021). "Functional studies have indicated the inhibition of STIM1 and ORAI1 in the metastasis of cancer cells." (PMID 33182378, 2020). "Aberrant overexpression of STIM1 or Orai1 and thus upregulated SOCE activity have been observed in several types of human cancers." (PMID 31252656, 2019). "In many cancer types including HCC, enhanced expression of STIM1 and Orai1 have been shown to enhance carcinogenesis including proliferation, migration and invasion processes." (PMID 31366337, 2019). "In cancer cells, SK3 co-localizes with Orai1 in plasma membrane lipid rafts where the complex operates independently of STIM1 as a constitutive Ca2+ entry pathway." (PMID 30558192, 2018). "In order to unravel the molecular underpinnings of constitutive Ca2+ entry, we undertook protein knockdown of Stim1, Orai1 and Orai3, that have been involved in SOCE activation in cancer cells, by using a siRNA silencing approach." (PMID 30123430, 2018). "Specifically, the dysregulation of distinct molecular components of SOCE, especially the STIM1 and Orai1 proteins and their homologues STIM2, Orai2, and Orai3, plays important roles in the pathophysiology of different types of cancer." (PMID 29951353, 2017).
cancer (continued). "Knockdown of Stim1 using siRNA remarkably enhanced cisplatin-induced apoptosis and ER stress in MG63/CDDP cells, thereby sensitizing cancer cells to cisplatin." (PMID 28326487, 2017). "The protein STIM1 andtheTRPC1 and Orai1 channels have been shown to be Store-Operated Channels (SOC) regulating cancer cell migration." (PMID 27102434, 2016). "More recently, it has been shown that serine residues of STIM1 are targets of extracellular-signal-regulated ERK1/2 and are involved in SOCE-dependent cancer cell migration." (PMID 27102434, 2016). "The discovery of STIM1 and Orai1 as the molecular components of SOCE has greatly advanced our understanding of the pathophysiological roles of SOCE in cancer." (PMID 25481035, 2015). "Since the identification of STIM1 and ORAI1 as the major players of SOC influx, numerous reports have emerged confirming their significant roles in cell migration and cancer metastasis." (PMID 25977921, 2015). "The importance of store-operated Ca2+ entry (SOCE) and the role of its key molecular regulators, STIM1 and ORAI1, in the development of cancer are emerging." (PMID 26257076, 2015). "We show that while deletion of either STIM1 or STIM2 inhibits the migration of cancer cells, deletion of both STIM isoforms (dKO) does not." (PMID 40719699, 2025). "The dysfunction of STIM1 and SERCA may lead to ER Ca2+ dyshomeostasis, which is closely related to many diseases, such as neurodegenerative disorders and cancer." (PMID 39594671, 2024). "These types of cancer exhibit an augmented SOCE response and overexpression of STIM1 and/or Orai1." (PMID 36982380, 2023). "All these cancer-related Orai1 mutants have been reported to lead to constitutive activity independent of STIM1." (PMID 36612099, 2022). "Recently, studies also reported that Orai remodelling was happened in cancer cell through Orai1 and Orai3 tetramer replacing Orai1 tetramer and did not need STIM1 activation." (PMID 36128650, 2022). "As is the case in cancer cells, modulation of the expression of STIM1/Orai1 has differential effects in other non-cancerous cell lines." (PMID 34069353, 2021). "STIM1 and ORAI1 have been reported to regulate invasion of cancer cells." (PMID 34155535, 2021). "STIM1 is therefore overexpressed in a hypoxic microenvironment and may contribute to the PDAC cell invasion, and thus, cancer progression." (PMID 34205590, 2021). "SOCE inhibition through STIM1 or ORAI1 knockdown inhibits the proliferation and metastasis of cancer cells, suggesting that SOCE may act as an oncogenic pathway." (PMID 34122115, 2021). "It is thus tempting to speculate that plasma membrane STIM1 and ARC channels may be important in cancer migration by sensing the tumour microenvironment." (PMID 32825277, 2020). "Furthermore, in very aggressive cancer cell lines (such as MDA-MB-231), STIM1 is overexpressed as compared to the MCF-7 cell line." (PMID 33511135, 2020). "Ineffective epithelial–mesenchymal transition (EMT) and metastasis suppression were observed in MDA-MB-231 and MCF-7 cell lines treated with transforming growth factor-β (TGF-β) in which STIM1 was knocked-down, proving a clue of the role of SOCE in TGF-β-induced cancer progression." (PMID 33511135, 2020). "In addition, we found that ODC suicide inhibitor DFMO inhibits expression of TRPC1 and STIM1 in CRC cells, thus, reversing Ca2+ channel remodeling in CRC and providing a mechanism for cancer chemoprevention by polyamine synthesis inhibition." (PMID 30642111, 2019). "While we previously showed that STIM1 specifically influences exogenous TGF-β-induced EMT, results in this work further our understanding of the biology of STIM family members in cancer cells and provide a rationale for potential precise targeting for cancer therapy." (PMID 31464639, 2019). "Although the function of STIM1-SOCE has been well characterized in non-excitable cells, the role of STIM1 in the regulation of cancer progression remains controversial and its clinical relevance is unclear." (PMID 31564210, 2019).
cancer (continued). "STIM1 was highly expression in NSCLC and promoted cancer proliferation by regulating cell cycle." (PMID 31564210, 2019). "Therefore, HDAC6 can be a cancer-specific target of malignant phenotypes mediated by STIM1-dependent SOCE, at least for cancers with upregulation of HDAC6 and STIM1." (PMID 31252656, 2019). "Recently, an increase in SOCE, related to the up‐regulation of Stim1, Orai1 or TRPC1 expressions, has been observed in several different kinds of tumours 6, 24, 30, indicating SOCs are the potential therapeutic target for treatment of cancers." (PMID 27878958, 2017). "Considering the important role of Stim1 and SOCE in ER stress and apoptosis, we proposed that Stim1 and SOCE might be involved in cisplatin resistance in cancer cells." (PMID 28326487, 2017). "Although, many studies demonstrated that STIM1 and SOCE play important functions in the regulation of many cancer progressions, their clinical relevance in HNSCC remains unclear." (PMID 28494008, 2017). "By contrast, STIM1 was expressed to similar degrees in all non-tumorigenic and cancer cell lines tested." (PMID 24797725, 2014). "It is therefore possible that different ion channels could be involved in affecting specific SOCE profiles as TRPC, Orai1 and STIM1 that can form heteromeric complexes or other members of the TRPC or ORAI families such as Orai3 in cancer cells." (PMID 23700407, 2013). "Unlike in SkM, STIM1 was unaltered upon cancer or temperature in BAT." (PMID 40237521, 2025). "The coordinated S‐acylation of Orai1 and STIM1 by zDHHC and APT enzymes might recruit both proteins to the same lipid domain to optimize Ca2+ fluxes, as suggested by studies linking enzymes involved in STIM‐ORAI1 S‐acylation/de‐acylation and cancer." (PMID 39429488, 2024). "Moreover, STIM1 and Orai1 have been reported to be overexpressed in cancer cells compared to their non-cancerous counterparts." (PMID 32235707, 2020). "Furthermore, since SOCE mediators such as STIM1 and ORAI1 are elevated in cancer cells and contribute to cancer aggressiveness, the exacerbation of SOCE might constitute a mechanism of resistance against TKI therapies." (PMID 29662626, 2018). "Our results also suggest that STIM1 plays an important role in TGF-β-induced suppression of cell proliferation and that specific small molecules targeting SOCE may be potential candidates for cancer therapy." (PMID 26919241, 2016). "The limitation of our study is that we could not clarify the STIM1 expression in cancer cells or that in stroma cells." (PMID 26543234, 2015). "In addition, STIM1 and ORAI1 inhibited NF-κB signaling and remodeled the tumor microenvironment by reducing the formation of M2 phenotype macrophages, possibly creating an unfavorable tumor microenvironment and inhibiting cancer development." (PMID 26257076, 2015). "However, STIM1 level is unlikely to be dominant in stroma cells because STIM1 was also highly expressed in cancer cells (data not shown)." (PMID 26543234, 2015). "To better probe STIM1β expression in cancer tissues, we set out to develop an antibody specifically targeting the PAD region of STIM1β that was absent in normal STIM1." (PMID 35076181, 2022). "STIM1 and ORAI1 are two basic components of SOC as a major pathway of calcium entry in non-excitable cells, especially in the cancer cells." (PMID 33182378, 2020). "While CM4620 is not currently utilized for cancer treatment, its remarkable ability to selectively inhibit STIM1/Orai1-mediated SOCE makes it highly promising for therapeutic applications in tumors with upregulated STIM1/Orai1 expression." (PMID 37932320, 2023). "In this part of the study, we investigated whether a potential interplay of SK3 and Orai1, as it occurs in specific cancer cell types, also applies to HEK 293 cells in the absence of STIM1." (PMID 34944977, 2021).
tumor (115 papers, 2006 to 2026). "Here, we found that TSPAN18 was an upstream regulator of STIM1-mediated Ca2+ signaling pathway, and was mainly overexpressed in tumor cells and associated with worse prognosis in PCa." (PMID 37542345, 2023). "Upregulation of STIM1 in primary cervical tumours was strongly linked with larger tumour size and elevated lymph node metastasis, and therefore poorer clinical outcomes." (PMID 37259313, 2023). "The suppression of such functions counteracted anti-tumor immunity by preventing the control of melanoma and colon carcinoma cell growth and their engraftment in STIM1- and STIM2- deficient cytotoxic T cells." (PMID 34201758, 2021). "STIM1 knockdown ML-1 cells were more susceptible to chemotherapeutic drugs, and significantly reduced tumor growth in Zebrafish." (PMID 34155535, 2021). "Knockdown or overexpression of STIM1 were associated with reduced and increased tumor growth, respectively." (PMID 32987945, 2020). "The critical roles of STIM1 and Orai1 proteins in tumor cell migration and the underlying molecular mechanisms have been extensively studied." (PMID 31252656, 2019). "The data herein indicate a straightforward correlation between STIM1-mediated Ca2+ signaling and wide-ranging signatures known to be associated with tumor aggression, and this implication was only present in COADs." (PMID 26543234, 2015). "In early investigations which were performed prior to the discovery of its role in Ca2+ signaling, STIM1 was described as a tumor suppressor for it causes growth arrest in human G401 rhabdoid tumor cells and human RD rhabdomyosarcoma cells." (PMID 23578185, 2013). "Patients with loss-of-function mutations in the CRAC channel genes ORAI1 or STIM1 are immunodeficient and are prone to develop virus-associated tumours." (PMID 23922331, 2013). "In addition, we previously demonstrated that the STIM1-dependent Ca2+ signaling pathway is implicated in EBV-driven tumor angiogenesis in NPC." (PMID 36677874, 2023). "Before STIM1’s role in Ca2+ influx was suspected, it was implicated that STIM1 could be a tumor suppressor." (PMID 36071984, 2022). "The pivotal proapoptotic role of STIM1/ORAI1 was first noted in pancreatic cancer where downregulation of ORAI1 or ectopic expression of its dominant-negative mutant reduced the susceptibility of tumor cells to apoptotic stimuli." (PMID 34572262, 2021). "Clinically, STIM1 has been correlated with poor prognosis in breast, colorectal, and lung carcinoma because its overexpression in patients’ tissues is associated with increased tumor size, lymphatic metastases, and other factors." (PMID 33511135, 2020). "Other affected genes are related to apoptosis (Ddx20, Ikbip), integrin-associated signal transduccion (Cd47), stress protein with antioxidant-associated tumor suppressive function (Tp53inp1/Trp53inp1), calcium signaling (Stim1), as well as those related to proliferation and survival (Lin28a)." (PMID 30742662, 2019). "In addition, activating ORAI1 through a genetically encoded light-inducible STIM1 fragment promotes tumour remission in a mouse model of DC cell-based immunotherapy." (PMID 29176619, 2017). "However, as just discussed, overexpression of STIM1 contributes to enhanced HCC cell proliferation and tumor growth, whereas decreased expression of STIM1 may be associated with HCC metastasis." (PMID 32987945, 2020). "Meanwhile, in experimental animal models given Stim1 overexpression, Ca2+ will increase, which is related to the activation of tumor cells." (PMID 40568493, 2025). "STIM1-mediated SOCE not only impacts tumor cells but also plays a role in the tumor microenvironment." (PMID 39281833, 2024). "In tumor growth, STIM1 stabilizes the Snail1 protein by activating the CaMKII/AKT/glycogen synthase kinase 3 beta pathway." (PMID 38344399, 2024).
tumor (continued). "In hypoxic environments, hypoxia inducible factor-1α (HIF-1α) increases PDAC progression by increasing stromal interaction molecule 1 (STIM1) expression in tumor tissue, potentially affecting the prognosis." (PMID 38532463, 2024). "The epithelial expression of STIM1 was observed in 60% of the normal pancreatic tissue cases, 73.9% of the adjacent non-tumor pancreatic tissue, and in all primary and metastatic PDAC groups." (PMID 38532463, 2024). "More importantly, immunofluorescence assays illustrated higher SLC7A11 expression was relevant to higher STIM1 expression compared with tumor tissues from HCC patients with low STIM1 expression." (PMID 39281833, 2024). "Recently, compelling evidence indicates the induction of tumor cell death can enhance the effects of antitumor immunotherapy, and that STIM1-induced tumor cell death can alleviate the resistance to antitumor therapy." (PMID 37932320, 2023). "The mechanisms by which STIM1 regulates apoptosis and autophagy in tumor cells have been more studied while the relationship between STIM1 and other types of tumor cell deaths (such as pyroptosis, ferroptosis, and cuproptosis) are still unclear." (PMID 37932320, 2023). "Since the discovery of STIM1, its roles in platelet aggregation, allergic reactions, autoimmune diseases, tumor cell death, and T-cell differentiation have been continuously investigated." (PMID 37932320, 2023). "Taken together, STIM1-mediated Ca2+ signaling actively participates in the regulation of the tumor’s invasiveness by modulating the cell adhesiveness." (PMID 36677874, 2023). "Altogether, targeting STIM1 to enhance the cytotoxic effect of T cells on tumor cells is a promising therapeutic strategy." (PMID 37932320, 2023). "Studies in the last decade have shown that STIM1 plays an important role in the induction of autophagy in tumor cells." (PMID 37932320, 2023). "Here, we review the basic structure, function and regulation of STIM1, summarize the signaling pathways through which STIM1 regulates tumor cell death, and propose the prospects of antitumor therapy by targeting STIM1." (PMID 37932320, 2023). "Of note, STIM1, an endoplasmic reticulum Ca2+ sensor, can drive tumor metastasis via the STIM1-dependent Ca2+ response or the modulation of focal adhesion turnover." (PMID 37542345, 2023). "An analysis of 10 HCC patients revealed that the protein expression of STIM1 and HIF-1α was positively correlated in patient tissues and was also associated with the tumour size in a xenograft mouse model." (PMID 35269437, 2022). "STIM1 and Orai1 were shown to regulate tumor cell migration partially involving the mediation of the focal adhesion." (PMID 36071984, 2022). "STIM1-KD ML-1 cells exhibited strongly reduced tumor growth, also confirmed by calculating the tumor area and fold change." (PMID 34155535, 2021). "This is inconsistent with the original identification of STIM1 as a candidate tumor suppressor as it maps to a region on Chromosome 11 that when deleted is associated with tumors." (PMID 34069353, 2021). "By injecting control ML-1 cells in the zebrafish xenograft experiments, the cells grew into a clear tumor; however, the STIM1-KD cells were unable to evoke tumor growth." (PMID 34155535, 2021). "VEGF drives tumor angiogenesis, and our experiments indicate that STIM1 is important for EBV-promoted angiogenic Ca2+ signaling in NPC." (PMID 34684224, 2021). "To date, there has been no report on the anti-angiogenic effects of exosomes derived from STIM1-KO-tumor cells." (PMID 33414420, 2021). "To prevent confounding from cell types with potential high STIM1 score, we further restricted the bulk sample with tumor purity of > 80% (based on immunohistochemistry (IHC)), resulting in 277 (of 471, 58.8%) patients." (PMID 33859736, 2021). "Matrigel plug assay in vivo showed that tumor angiogenesis was suppressed in Exo-STIM1-KO, but promoted when miR-145 antagomir was added." (PMID 33414420, 2021).